KLF6 (KLF transcription factor 6)
Diseases named in the same sentence as KLF6 in open-access papers (continued):
Sharing a sentence is not in itself a finding about the gene and the disease.
gastric cancer (14 papers, 2009 to 2025). A primary or metastatic malignant neoplasm involving the stomach. "On the other hand, downexpression of KLF6 was also frequently observed in breast and gastric cancers and non-small lung cancer." (PMID 29854578, 2018). "Although miR-181a has been reported to promote gastric cancer by negatively regulating the KLF6 tumor suppressor and the immune system, most studies indicate that miR-181a has anti-tumor effects." (PMID 23516523, 2013). "According to some studies, the deletion and mutation of KLF6 and PDCD4 were associated with gastric cancer and colon carcinogenesis, since the downregulation of these cancer suppressor genes were found to promote over-proliferation of cells." (PMID 23825654, 2013). "MicroRNA-181a can promote gastric cancer by negatively regulating tumor suppressor KLF6." (PMID 28388883, 2017). "Interestingly, they demonstrate that miR-181a functions as a tumor promoter in gastric cancer by repressing the expression of KLF6." (PMID 24378751, 2013). "In gastric cancer, miR-200c specifically binds to the 3′-UTR of FN1 and KLF6, thereby downregulating their expression and affecting the proliferation, migration, and invasion of gastric cancer cells." (PMID 39859424, 2025). "We focused on KLF6 and KLF15 as the interaction between miR-181a-5p and KLF6 has been previously demonstrated in gastric cancer, and KLF6 and KLF15 were putative tumor suppressors in BC." (PMID 32998707, 2020).
glioblastoma (14 papers, 2008 to 2024). The most malignant astrocytic tumor (WHO grade IV). "Future work is required to elucidate the roles of cholesterol metabolism in oRG proliferation and neurogenesis, particularly in light of clinical association of KLF6 to glioblastoma, in which sustained cholesterol synthesis impacts tumor cell growth." (PMID 39114968, 2024). "We identified several previously reported single-nucleotide polymorphisms (data not shown) and a new mutation (391 G/A, V to M) in one patient (frequency: 0.02), confirming that KLF6 is rarely mutated in glioblastoma." (PMID 28166199, 2017). "We demonstrate that KLF6 is frequently inactivated in glioblastoma and propose KLF6 deletion as a new mechanism underlying NF-κB signaling increase in this tumor type." (PMID 28166199, 2017). "Given previous contradictory results regarding KLF6 mutations in glioblastoma, we sequenced the KLF6 sequence upstream of the ATG (431 bp), CDS exons 1–4 and intron–exon boundaries in 45 glioblastoma samples." (PMID 28166199, 2017). "Together, our study identifies a new mechanism by which KLF6 regulates NF-κB signaling, and how this mechanism is circumvented in glioblastoma through KLF6 loss." (PMID 28166199, 2017). "Our in vivo results point toward KLF6 as a tumor suppressor in glioblastoma inhibiting NF-κB activity, causing loss of stemness and promoting differentiation." (PMID 28166199, 2017). "To date, some reports have described that KLF6 overexpression results in the upregulation of differentiation markers associated to a cell proliferation inhibition and cellular senescence in liposarcoma and glioblastoma." (PMID 31824948, 2019). "KLF6 whose reduction advances NFκB signaling in glioblastoma is found to be the common TF between TR astrocyte and NFO." (PMID 34976314, 2022). "In glioblastoma, loss of several factors, including PTEN, NF1 and KLF6, as well as increased activity/expression of others, including PIN1, MLK4 and microRNA-30e, have all been shown to contribute to NF-κB activation." (PMID 35922651, 2022). "KLF6 expression attenuates the tumorigenicity of glioblastoma multiforme cells both in vitro and in vivo and is able to inhibit cellular transformation induced by a variety of oncogenes." (PMID 31824948, 2019). "Gene expression of klf6 is significantly upregulated by overexpression of ATF3 in glioblastoma cells." (PMID 28250971, 2017). "In this study we have identified a previously unappreciated NF-κB regulatory pathway that involves transactivation of NF-κB-negative regulatory genes by the tumor suppressor KLF6 in glioblastoma." (PMID 28166199, 2017). "Here, we report a new mechanism of NF-κB activation in glioblastoma through depletion of the KLF6 tumor suppressor." (PMID 28166199, 2017). "KLF6 is heterozygously deleted in 74.5% of the analyzed glioblastomas and predicts unfavorable patient prognosis suggesting that haploinsufficiency is a clinically relevant means of evading KLF6-dependent regulation of NF-κB." (PMID 28166199, 2017). "In contrast, KLF6 was able to transactivate multiple genes that negatively regulated the NF-κB pathway, thereby decreasing the nuclear localization of NF-κB and downregulating the expression of its target genes in glioblastoma." (PMID 37391422, 2023). "It was found for the first time in 2004 that KLF6 expression in glioblastoma multiforme (GBM) can inhibit the growth and tumorigenicity of glioblastoma which could then activate the p21Cip1/Waf1 promoter both in vitro and in vivo." (PMID 33816511, 2021). "It has been reported that in glioblastoma, agomir-101 combined with sh-KLF6 can reduce the size of tumours in nude mice more effectively than transfection of either agomir-101 or sh-KLF6 alone and that the survival rate of nude mice is highest in the co-transfection group." (PMID 29391048, 2018). "We then assessed KLF6 and BCL6 associations with survival in 406 patients with glioblastoma." (PMID 28166199, 2017).
glioblastoma (continued). "Because deletion of chromosome 10p15 is one of the most common chromosomal alterations in gliomas, KLF6 LOH is detected in 90% of glioblastoma samples, without evidences of KLF6 somatic mutations." (PMID 20119532, 2009). "Still, KLF6 expression is attenuated in human glioblastomas, when compared to primary astrocytes." (PMID 20119532, 2009). "KLF6 mutants loose their ability to reduce growth rate of glioma cells, whereas KLF6 SV1 expression is increased in glioblastomas to sustain cell proliferation." (PMID 20119532, 2009). "We show that KLF6 overexpression often reduced NESTIN and increased neural genes expression in glioblastoma cells and LN229-KLF6-wt derived tumors, suggesting that KLF6-wt could reduce stemness and induce neural differentiation." (PMID 28166199, 2017). "Consistent with the high KLF6 heterozygous deletion frequency observed in our analysis, KLF6 expression in glioblastoma was reduced compared with normal brain samples (non-malignant cortical samples obtained from epilepsy surgery, NB)." (PMID 28166199, 2017). "In this sense, it has been shown that prolonged expression of KLF6-wt, but not KLF6-sv1, induced a senescent-like phenotype in two cell lines derived from glioblastoma: LN229 (glioblastoma cell line) and BTSC23." (PMID 31824948, 2019).
lung carcinoma (13 papers, 2009 to 2025). "In addition, a potential involvement of KLF6 IVS1-27G>A polymorphism is associated with lung cancer risk." (PMID 20119532, 2009). "For example, KLF6 was found to be inactivated and/or expression-downregulated in lung cancer, colorectal cancer, liver cancer, and some other cancers." (PMID 36615000, 2022). "In lung cancer cell lines, KLF6 SV1 protects cells from apoptosis, and its targeted reduction induces apoptosis." (PMID 20119532, 2009). "However, KLF6 is mainly located in the nucleus in other cell line like A 549 derived from lung carcinoma (V. Andreoli and J.L. Bocco, unpublished)." (PMID 20126619, 2010). "In this paper, KLFs have been summarized via systematic reviews, with either a promoting (KLF4 ∼ KLF8, KLF15) or an inhibiting (KLF2 ∼ KLF6, KLK9 ∼ KLF12 and KLF17) roles, which should be useful to monitor lung cancer progression or understand its mechanisms." (PMID 38560274, 2024). "Among the KLFs, the clear promoting effects on lung cancer were KLF5, KLF7, KLF8, and KLF15, as well as KLF4 and KLF6, which have dual functions." (PMID 38560274, 2024). "In contrast to wild-type KLF6, KLF6-SV1 promoted the expression of TWIST1 and C-C motif ligand 2, which promoted the involvement of EMT in the metastasis of lung cancer cells." (PMID 36761967, 2023). "We conclude that although KLF6 promotes AGT gene transcription when oncogenic K-Ras is expressed in normal cells, HMGA1 promotes AGT expression in lung cancer cells expressing oncogenic K-Ras." (PMID 33380422, 2021). "In lung cancer, TFP inhibited FOXO1 nuclear export and restored sensitivity to Erlotinib resistance by modulating the KLF6/FOXO1 signaling cascade in both cell culture and xenograft models." (PMID 31572198, 2019). "Enforced expression of KLF6 resulted in NSLC-derived cells apoptosis, while PKC activates KLF6 to mediate lung cancer-derived cell lines growth inhibition." (PMID 20119532, 2009). "In contrast to what we found in normal cells after overexpression of K-RasG12V, AGT expression was not mediated by the transcription factor KLF6 in lung cancer cells, in which KLF6 expression was dramatically downregulated." (PMID 33380422, 2021). "The same applies to another three genes KLF6 (Krüppel-like zinc finger transcription factor), MSH5 (MutS protein homolog 5) and ACTA2 (Alpha-smooth muscle actin), which were also found to be associated with lung cancer by several previous GWASs, albeit not as prominently as CHRNA5 and TERT." (PMID 27323854, 2016).
liver cancer (12 papers, 2013 to 2023). An epithelial or non-epithelial malignant neoplasm that arises from the liver. "Klf6 is a gene responsible for tumorigenesis, and the loss of the Klf6 SE was found to inhibit the proliferation of liver cancer cells by upregulating miR-1301." (PMID 34011395, 2021). "Thus, we and others demonstrated that KLF6 and its splicing variants play a critical role in liver cancer." (PMID 24378751, 2013). "The full-length KLF6 (KLF6-FL) is a tumour-suppressive isoform, while KLF6 splice variant 1 (KLF6-SV1) possesses an oncogenic effect in liver cancer." (PMID 35427215, 2022). "Our results on the KLF6/p21/Rb axis contribute to explain the growth inhibitory effect of 400 μM metformin on the human hepatic cancer HepG2." (PMID 30774659, 2019). "More importantly, KLF6 invalidation results in cell cycle progression inhibition and apoptosis of liver cancer cells." (PMID 24378751, 2013). "Further work is needed to identify the factors that bind to KLF6 3'UTR to regulate its expression in liver cancer-derived cell lines." (PMID 24378751, 2013). "KLF6 mRNA decay was significantly faster in human liver cancer cell lines (Hep3B and HepG2) as compared to immortalized human hepatocytes (IHH) (student t test, p = 0.008)." (PMID 24378751, 2013). "Another study found that KLF6 could protect liver cancer from apoptosis to accelerate its progression." (PMID 36615000, 2022). "Disruption of KLF6-SE has been shown to inhibit the growth of liver cancer cells." (PMID 33712565, 2021). "Further work is needed to identify the miRNAs and/or the proteins that bind to KLF6 UTR to regulate its expression in liver cancer-derived cell lines, and therefore may contribute to cell cycle alteration of liver-derived cancer cells." (PMID 24378751, 2013). "Interestingly, KLF6 mRNA was highly unstable in liver cancer-derived cell lines as compared to normal hepatocytes." (PMID 24378751, 2013). "In the present work, we asked whether KLF6 3'UTR may be responsible for down regulation of KLF6 mRNA in HCC, and therefore may contribute to cell cycle alteration of liver cancer cells." (PMID 24378751, 2013). "MiR-1301 could enhance liver cancer cell migration and angiogenesis by targeting the 154-bp sequence within KLF6-FL rather than KLF6-SV1." (PMID 35427215, 2022).
clear cell renal cell carcinoma (10 papers, 2019 to 2023). "In a 2020 study, the lncMIR4435-2HG/miR-513a-5p/KLF6 axis was studied, which up-regulated clear cell renal cell carcinoma KLF6, proven to be a typical inhibitor of various localized tumours, including prostate and colorectal." (PMID 36447000, 2023). "This interpretation is consistent with data showing that CBX4 interacted with HDAC1 to repress the tumor suppressor KLF6 in clear cell renal carcinoma while knockdown of HDAC1 restored KLF6 function." (PMID 35251476, 2022). "Here we report that Kruppel like factor 6 (KLF6), a transcription factor of the zinc finger family, regulates lipid homeostasis in clear cell renal cell carcinoma (ccRCC)." (PMID 30858363, 2019). "Moreover, a previous study identified the KLF6 gene as a tumor suppressor gene; for example, KLF6 inhibited the proliferation and promoted the apoptosis of clear cell renal cell carcinoma (ccRCC) cells as a target gene of both miR-543 and miR-181a." (PMID 32581828, 2020). "Furthermore, miR-181a overexpression contributes to clear cell renal cell carcinoma (ccRCC) progression via modulating Krüppel-like factor 6 (KLF6) expression; targeting miR-181a may have therapeutic potential in this context." (PMID 33299464, 2020). "Kruppel like factor 6 (KLF6), a transcription factor of the zinc finger family, has been reported to play an important role in lipid homeostasis regulation in clear cell renal cell carcinoma." (PMID 34504794, 2021).
colorectal cancer (10 papers, 2008 to 2025). A primary or metastatic malignant neoplasm that affects the colon or rectum. "KLF6 is a tumor suppressor based on its inactivation and somatic mutations in a variety of cancers such as prostate, gastric, ovarian, breast, liver, and colorectal cancer." (PMID 27690088, 2016). "Down-regulation of KLF6 may contribute to the development of solid human cancers, and inactivating it may result in the development of colorectal cancer as a primary or common occurrence." (PMID 31724937, 2019). "An alternative splicing isoform of KLF6, KLF6-SV2, has been shown to induce apoptosis in colorectal cancer by increasing the expression of p21 and a Bcl-2 apoptotic protein Bax." (PMID 36761967, 2023). "In colorectal cancer, SIOMICS predicted five shared motifs, which were similar to the motif of the TFs SP1, the CAC-binding protein, TFAP2A (AP-2), KLF6 (GBF), and EGR1 (KROX), respectively (the names in parentheses are the corresponding TRANSFAC TF names)." (PMID 28684851, 2017). "LOH of KLF6 locus at chromosome 10p15 contributes to the development of non-polypoid colorectal carcinoma, and in the invasion step from an intra-mucosal to an invasive carcinoma." (PMID 20119532, 2009).
COVID-19 (10 papers, 2020 to 2023). A disease caused by infection with severe acute respiratory syndrome coronavirus 2. "In cohort 2 our results included SNPs in the following genes, Kruppel Like Factor 6 (KLF6) that encodes for an inflammation regulator with high expression in the macrophages in BAL from grievously ill COVID-19 patients." (PMID 36143338, 2022). "They identified neutrophils (IFITM2, IFITM1, H3-H3B, SAT1 and S100A8) and macrophage cluster-1 (CCL8, CCL3, CCL2, KLF6 and SPP1) as the main immune cell subsets associated with severe COVID-19 cases." (PMID 34109284, 2021). "Among the identified gene signatures, IFITM2, IFITM1, H3F3B, SAT1, and S100A8 gene signatures were highly associated with neutrophils, while CCL8, CCL3, CCL2, KLF6, and SPP1 were associated with macrophage cluster-1 in severe-COVID-19 patients." (PMID 33138195, 2020). "Particularly, many inflammation genes, such as C5AR1, CD55, CSF3R, CXCL8, FPR1, KLF6, and NFKB1A, were significantly upregulated in Neu and Mono cells of the bone marrow of COVID-19 patients." (PMID 37087411, 2023). "The macrophage cluster-1-derived signature (CCL8, CCL3, CCL2, KLF6, and SPP1) was confirmed to be significantly higher in severe cases of COVID-19 compared to control and mild cases." (PMID 33138195, 2020). "Finally, higher levels of KLF6, a transcription factor induced by TGF-β in DCs, was increased in pDCs in BAL from severe COVID-19 patients, while the MHC class II molecule HLA-DQA2 displayed lower transcript levels, in line with lower protein levels of HLA-DR detected on circulating pDCs." (PMID 33479167, 2021).
endothelial dysfunction (8 papers, 2020 to 2025). In vascular diseases, endothelial dysfunction is a systemic pathological state of the endothelium (the inner lining of blood vessels) and can be broadly defined as an imbalance between vasodilating and vasoconstricting substances produced by (or acting on) the endothelium. "KLF6 contributes to endothelial dysfunction and tissue repair, and SRGN amplifies inflammatory responses through cytokine release." (PMID 41303672, 2025). "Previous studies showed that KLF6 is involved in endothelial dysfunction and regulates macrophage-mediated inflammation, providing a link between KLF6 and immune cells in IA." (PMID 39215680, 2024). "Azilsartan attenuates oscillatory shear stress-induced endothelial dysfunction and inflammatory responses by upregulating KLF6." (PMID 37391422, 2023). "Previous studies have demonstrated that knockdown or inhibition of Klf6 expression could reduce macrophage filtration, reverse endothelial dysfunction, and lower inflammatory factor expression." (PMID 36911738, 2023). "Different stimuli related to endothelial dysfunction, such as vascular stress, oxysterols, and inflammation, have been reported to upregulate Eng gene transcription via transcription factors Kruppel Like Factor 6 (KLF6), liver X receptor alpha (NR1H3) and NF-κB p65 (RELA)." (PMID 36160139, 2022).
non-small cell lung carcinoma (8 papers, 2008 to 2023). A group of at least three distinct histological types of lung cancer, including non-small cell squamous cell carcinoma, adenocarcinoma, and large cell carcinoma. "However, in a non-small cell lung cancer study, PKC has been associated with KLF6 activation following PMA-mediated growth arrest." (PMID 23977008, 2013).
acute myeloid leukemia (7 papers, 2013 to 2024). Acute myeloid leukemia (AML) is a group of neoplasms arising from precursor cells committed to the myeloid cell-line differentiation. "Additionally, KLF6 has been implicated in the transforming activity of the oncogenic fusion protein AML-1-ETO in Acute Myeloid Leukemia (AML)." (PMID 38730619, 2024). "The pro-oncogenic fusion protein RUNX1-ETO upregulated the expression of KLF6 in acute myeloid leukaemia." (PMID 32998281, 2020). "KLF6 was highly expressed in acute myeloid leukaemia, renal cancer of clear cell and papillary subtypes, glioblastoma multiforme and pancreatic cancer." (PMID 32998281, 2020). "For example, KLF6 was identified as not only the most downregulated transcription factor with aging, but also as aberrantly methylated in acute myeloid leukemia (AML)." (PMID 35318612, 2022). "However, KLF6 gene is identified as having a probable epigenetic mechanism involved in the proliferation of many kinds of tumor cells, and in the reduction in neutrophilia of acute myeloid leukemia, as it is a known tumor suppressor." (PMID 31242656, 2019). "For example, KLF6 is highly expressed in acute myeloid leukaemia and can be regulated by the pro-oncogenic fusion protein RUNX1-ETO to promote the progression of acute myeloid leukaemia." (PMID 36615000, 2022).